HEG1 (heart development protein with EGF like domains 1)
Diseases named in the same sentence as HEG1 in open-access papers (continued):
Sharing a sentence is not in itself a finding about the gene and the disease.
malignant pleural mesothelioma (1 paper, 2025). A malignant neoplasm that arises from mesothelial cells in the pleura and shows a diffuse growth pattern. "The glycoform of heart development protein with EGF‐like domains 1 (HEG1) recognized by the SKM9‐2 monoclonal antibody is a useful diagnostic marker for malignant pleural mesothelioma (MPM)." (PMID 40525709, 2025). "The purpose of this study is to investigate sulfation modification of the glycan structure decorating HEG1, one of the diagnostic markers of malignant pleural mesothelioma (MPM), in MPM." (PMID 40525709, 2025).
pulmonary disease (1 paper, 2022). "In this study, HEG1 in lung tissues and cell lines of LUAD were significantly downregulated compared to benign pulmonary disease tissues and alveolar epithelial cells (p < 0.05)." (PMID 35950222, 2022).
sarcomatoid carcinoma (1 paper, 2025). A malignant epithelial neoplasm characterized by the presence of spindle cells and anaplastic morphologic features. "The twenty-one lung sarcomatoid carcinomas did not exhibit any cytoplasmic HEG1 staining." (PMID 40091315, 2025).
sarcomatoid lung carcinomas (1 paper, 2025). "Differently, in the setting of spindle cell neoplasms, HEG1 has shown good diagnostic specificity but poor sensitivity in the differential diagnosis between PSM and sarcomatoid lung carcinomas." (PMID 39941848, 2025).
serous ovarian tumors (1 paper, 2008). "For example, TMEM158, HEG1, PLOD2 and ATP13A3, were recently found differentially expressed greater than 3-fold in a comparative analysis of primary cultures of normal ovarian surface epithelial cells and malignant serous ovarian tumors." (PMID 18687136, 2008).
cancer (14 papers, 2008 to 2026). A tumor composed of atypical neoplastic, often pleomorphic cells that invade other tissues. "The objective of this study was to analyze the diagnostic role of HEG homolog 1 (HEG1) in cancers affecting the serosal cavities." (PMID 41656400, 2026). "The under-expressed HEG1 encodes protein participating in the cancer metastasis process, while the protein encoded by the downregulated INTS2 belongs to a key regulator of RNA polymerase II-mediated transcription integrator complex." (PMID 37894381, 2023). "These processes are associated with tumor development and progression, so HEG1 may play a crucial role in cancer cell growth." (PMID 37835810, 2023). "To examine the effect of HEG1 KD on cancer cell proliferation in vivo, we performed Ki67 IHC staining in treated tumors." (PMID 37024475, 2023). "In this study, HEG1 expression in a TCGA pan‐cancer dataset and GTEx database were obtained from the GEPIA platform, while UALCAN database was adopted to verify the findings." (PMID 35950222, 2022). "ReactomeFIViz enrichment analysis in Cytoscape showed that two genes (HEG1 and PLSCR4) have evidence of their association with the acquisition of cancer characteristics." (PMID 36101460, 2022). "Of 179 HEG1-positive carcinomas, 172 expressed the epithelial marker claudin-4." (PMID 41656400, 2026). "In the report of HCC, the authors used the same antibody against HEG1, which suggests that the differences in results may be due to the type of cancer cells." (PMID 37835810, 2023). "Kaplan–Meier analysis revealed that the membranous HEG1-positive group had significantly long recurrence-free survival (RFS) (p < 0.01) and cancer-specific survival (p = 0.01)." (PMID 37835810, 2023). "As the results, HEG1 was decreased in cancer mass and serum from patients with LUAD, while the low HEG1 portends a shorter OS and poorer outcomes for LUAD." (PMID 35950222, 2022). "Therefore, it is recommended to use panels consisting of at least two carcinoma markers (such as pCEA BER-EP4, MOC-31, Claudin 4, HEG1) and two mesothelial markers (such as WT1, calretinin, CK5/6, D2-40)." (PMID 39407894, 2024).
tumor (13 papers, 2018 to 2025). "The results showed that membranous HEG1 expression in tumor cells was associated with long CSS and RFS in patients with BC." (PMID 37835810, 2023). "Most HEG1 signals found on the apical membrane of tumor cells were colocalized with 294‐1B1 signals." (PMID 40525709, 2025). "HEG1 protein expression in tumor cells was evaluated separately for membrane and cytoplasmic staining using immunohistochemistry." (PMID 37835810, 2023). "ROC curve analysis showed that HEG1 had an AUC of 0.903 (95% CI:0.776–1.000, p < 0.001) to distinguish tumor stage with a cut‐off value of 0.257, and the sensitivity and specificity were 92.3% and 83.3%, respectively." (PMID 35950222, 2022). "Overall, these data suggested that HEG1 can be used as a biomarker for LUAD in monitoring tumor recurrence and determining patient prognosis." (PMID 35950222, 2022). "We conducted GSEA between high and low HEG1 expression datasets to determine the biological functions activated in tumor progression." (PMID 35950222, 2022). "HEG1 staining was observed in the membrane and cytoplasm of the tumor cells." (PMID 37835810, 2023). "Therefore, the prognostic significance of HEG1 expression in various other tumor types remains unexplored." (PMID 37835810, 2023). "The results showed that patients with an advanced tumor stage had lower HEG1 mRNA expression than the other group (p = 0.025) and this manifested that the patients with low HEG1 expression may have a relatively malignant procession." (PMID 35950222, 2022). "As the expression of HEG1 was regulated by tumor‐suppressor genes and oncogenes concurrently, HEG1 expression could vary in different tumors." (PMID 35950222, 2022). "It is well‐known that the abnormality in those activities is closely related to tumor development and progression, which indicates that HEG1 might play some critical role in the development of carcinoma." (PMID 35950222, 2022). "Moreover, compared with other groups, patients with advanced tumor stage had lower HEG1 mRNA expression levels (p = 0.025), which were negatively correlated with Ki67 index in tumor tissues (r = −0.427, p = 0.033)." (PMID 35950222, 2022). "Overall, the findings demonstrated that HEG1 was downregulated in LUAD tissues when compared to paired adjacent normal tissues and that the low HEG1 expression may have a relationship with the degree of tumor malignancy." (PMID 35950222, 2022). "Moreover, our results indicated that HEG1 has great clinical significance in the early diagnosis, recurrence monitoring of adenocarcinoma, and has potential to be widely used in clinical practice as a tumor biomarker for diagnosis and prognosis of LUAD." (PMID 35950222, 2022). "In contrast, downregulated genes included at least 15 candidate tumor suppressors (e.g., CDH18, HEG1)." (PMID 41278279, 2025). "The serum tumour marker, CA19-9 and the mesothelial cancer tumour marker, sialylated HEG1, are well-known examples for glycan alteration of MUC1 accompanied by malignant transformation." (PMID 37031283, 2023). "Moreover, we found that HEG1 may be related to the degree of tumor differentiation." (PMID 35950222, 2022). "Moreover, knockdown of HEG1 markedly overcame the OXA resistance induced by PRMT3 OE in HepG2 cells in vivo as shown by weekly measurement of tumor volumes and tumor weights at the endpoint." (PMID 37024475, 2023). "Although the authors found HEG1 expression in the tumor cell membrane and/or cytoplasm, their study did not describe the subcellular localization of HEG1." (PMID 37835810, 2023). "Given that morphological plasticity is a key determinant of cell migration, many of the identified genes were found to have a role in promotion of tumor cell migration and invasion, including ECM production and mesenchymal state induction (HEG1, BZW2, DCAF13, SQLE, PKIA)." (PMID 35879361, 2023).
tumor (continued). "The tumor cells were positive for AE1/AE2, calretinin, WT-1, D2-40, HEG1, EMA, BAP1, and MTAP and negative for carcinoembryonic antigen, MOC-31, Ber-Ep4, ER, PgR, TTF-1, claudin 4, and desmin." (PMID 36896044, 2023).
adenocarcinoma (2 papers, 2022 to 2025). A common cancer characterized by the presence of malignant glandular cells. "To verify the reliability of this method, we further investigated the association between the expression of HEG1 and CEA, the typical biomarker for adenocarcinoma." (PMID 35950222, 2022).
Cardiovascular Disease (2 papers, 2020 to 2021). "In mice with Heg1 gene mutation, the vascular endothelial barrier is weakened, resulting in cardiovascular diseases such as sepsis, atherosclerosis, and multiple sclerosis." (PMID 33198188, 2020).
HEG1 also shares sentences with these, for which no sentence is quoted: breast carcinoma (2 papers); osteosarcoma (2); biphasic mesothelioma (1); bladder cancer (1); cerebral cavernous malformation (1); congenital cardiomyopathy (1); diabetes (1); endothelial dysfunction (1); Ewing sarcoma (1); gastric cancer (1); lung (1); lung adenosquamous carcinoma (1); metastatic carcinoma (1); neonatal diabetes mellitus (1); non-alcoholic fatty liver disease (1); osteopetrosis (1); pancreatic adenocarcinoma (1); peritoneal mesothelioma (1); sarcomatoid mesothelioma (1); serous carcinoma of the ovary (1); spindle cell neoplasm (1); squamous cell carcinoma (1); thyroid carcinomas (1); type 2 diabetes (1).